MIB1 (MIB E3 ubiquitin protein ligase 1)
Diseases named in the same sentence as MIB1 in open-access papers (continued):
Sharing a sentence is not in itself a finding about the gene and the disease.
astrocytomas (5 papers, 2011 to 2024). "In addition to the direct correlation between DJ-1 and grading, our results also demonstrated a strong association between DJ-1 and MIB-1 LI in the studied cases of astrocytomas." (PMID 23902708, 2013). "Kaplan- Meier survival showed that the astrocytoma cases with MIB-1 LI ≥ 10.1 were associated with shorter median survival (16m ± 2.207, 95% CI: 11.674 -20.326), when compared to those cases with MIB-1 LI < 10.1 which were associated with longer median survival(68m ± 9.785, 95% CI: 48.822 -87.178)." (PMID 23902708, 2013). "The study suggests that MIB1 mutation is present in 1.39% of AACR GENIE cases, with colon, lung adenocarcinoma and astrocytoma and colorectal adenocarcinoma having the greatest prevalence of mutation." (PMID 37746636, 2023). "The wide range of Mcm2 PIs points to possible overlap of values between astrocytomas of various malignancy grades comparable with that of Ki67/MIB-1 immunostaining." (PMID 23618321, 2013). "The research investigates the expression of MIB-1 and DJ-1 in different grades of astrocytomas and evaluates the possible prognostic role of DJ-1 in these tumors in relation to other prognostic parameters including the MIB-1 labeling index." (PMID 23902708, 2013). "Multivariate survival analysis was also performed to study the effect of the different factors including age, gender, DJ-1, MIB-1 LI and necrosis (in GBMs only) on the overall survival in each grade of astrocytomas." (PMID 23902708, 2013). "Many studies have focused on the proliferative activity in astrocytomas especially ki-67/MIB-1 labeling index (LI)." (PMID 23902708, 2013). "Most of the studies have found significant differences in MIB-1 labeling indices between low and high grade astrocytomas." (PMID 23902708, 2013). "Nevertheless, a MIB-1 LI greater than 10 may serve as a commonly used value to express a more aggressive phenotype of astrocytomas." (PMID 23902708, 2013). "Accordingly, Mcm2 does not seem to have any advantages over Ki67/MIB-1 in the evaluation of the prognosis of grade II astrocytomas." (PMID 23618321, 2013). "The effect on patient’s overall survival in high grade astrocytomas was restricted to DJ-1 rendering it a poor prognostic indicator independent of other factors including MIB-1 LI." (PMID 23902708, 2013). "In our hands Mcm2 immunostaining has no advantage over Ki67/MIB-1 in the evaluation of grade II astrocytomas." (PMID 23618321, 2013). "The LIs displayed a wide range of values that overlap with indices in both grade II and grade IV astrocytomas, and is regarded as the main reason for Ki-67/MIB-1 not being included in the routine histopathological diagnosis of astrocytic tumours." (PMID 21609421, 2011). "The present study shows that MIB-1 LI could not also provide an independent role for predicting survival when Cox regression analysis was carried out for each grade of astrocytoma." (PMID 23902708, 2013).
brain tumors (5 papers, 2014 to 2024). "The intensity of the ASL-MRI signal correlates with vessel density and the MIB1 index, which are indicators of cell proliferation, thus aiding the diagnosis and treatment evaluation of brain tumors based on TBF measured by ASL-MRI." (PMID 39310434, 2024). "Previous studies of brain tumors reported relationships between high FA values and high cellularity, high WHO grades, and high MIB‐1 LIs." (PMID 37644780, 2023). "We began by looking at a combination of FISH and MIB-1 immunostaining since the proliferation index, as measured with the MIB-1 antibody, is routinely reported on most brain neoplasms and the chromosome 1p and 19q status is routinely determined for all oligodendroglial tumors in our laboratory." (PMID 24949947, 2014).
diffuse astrocytoma (5 papers, 2013 to 2024). A low-grade (WHO grade II) astrocytic neoplasm. "The aim of this study was to investigate the prognostic role of Mcm2 expression in a series of diffuse astrocytomas WHO grade II and to correlate it with histopathological features, mitoses, and Ki67/MIB-1 immunostaining." (PMID 23618321, 2013). "Comparisons of the T/N ratios of 11C-MET PET and the MIB-1 LI have found a significant correlation in diffuse astrocytoma but not in oligodendroglial tumor." (PMID 28567708, 2017). "This study was designed to evaluate the prognostic significance of the proliferation marker Mcm2 in a series of diffuse astrocytoma WHO grade II with thorough follow-up, and to compare its expression with histopathological features, mitoses, as well as Ki67/MIB-1 immunostaining." (PMID 23618321, 2013). "This study was designed to investigate the prognostic significance of the proliferative marker Mcm2 (minichromosome maintenance protein 2) in diffuse astrocytomas WHO grade II and correlate the findings with histopathology, mitoses, and Ki67/MIB-1 immunostaining." (PMID 23618321, 2013).
pituitary adenomas (5 papers, 2014 to 2024). "MIB-1 labeling indices of these pituitary adenomas ranged from 0.6 to 1.8%." (PMID 26339240, 2015). "The MIB1 LI was evaluated in 54 (91.5%) of the 59 study group patients: in all of the pituitary macroadenomas and in 34 of 39 microadenomas, i.e. in all the cases with a previously confirmed ACTH-staining pituitary adenoma." (PMID 26811407, 2016).
skull base meningioma (5 papers, 2022 to 2025). A meningioma that arises from the skull base. "The intake of low-dose ASA (adjusted odds ratio (OR): 2.60, 95% confidence interval (CI): 1.03–6.55, p = 0.04) was independently and significantly associated with a decreased MIB-1 labeling index (<5%) in female non-skull-base meningioma patients aged 60 years or older." (PMID 36077817, 2022). "Therefore, it is very likely that low-dose ASA treatment significantly modifies the inflammatory tumor microenvironment by decreasing the MIB-1 labeling index in female elderly non-skull-base meningioma patients, leading to a reduced risk of symptomatic epilepsy." (PMID 36077817, 2022). "This retrospective study shows that MIB-1 as well as mitotic count are good predictors for progression-free survival in skull-base meningiomas." (PMID 36230518, 2022). "MIB-1 as well as MC were good predictors for PFS in skull-base meningiomas." (PMID 36230518, 2022). "MIB-1 as well as MC are good predictors for PFS in skull-base meningiomas." (PMID 36230518, 2022). "We identified that there is a significant difference regarding MIB-1 labeling index in female elderly (≥60 years) non-skull-base meningiomas with or without low-dose ASA treatment." (PMID 36077817, 2022).
colorectal cancer (4 papers, 2013 to 2024). A primary or metastatic malignant neoplasm that affects the colon or rectum. "A distinct scaffolding function was observed in CEMIP, mediating GRAF1 and MIB1 coordination, thereby instigating metastatic events in colorectal cancer through CDC42/MAPK pathway activation." (PMID 39624211, 2024). "In colorectal cancer Mcm2 was shown to be a stronger indicator of proliferative cells than Ki67/MIB-1." (PMID 23618321, 2013).
infiltrating ductal carcinoma (4 papers, 1999 to 2014). "Primary tumour cells were isolated from breast tissue of a patient with an infiltrating ductal carcinoma (IDC) and with the following histologic features: moderately differentiated, G2, pT2, pN1a, MIB-1 (KI-67) proliferation index 21%, ER+/PR+, HER2-." (PMID 22759679, 2012). "We observed that MIB-1 is a reliable independent prognostic indicator for ER negative infiltrating ductal carcinoma in this study." (PMID 24586570, 2014).
invasive breast carcinoma (4 papers, 1996 to 2022). A carcinoma that infiltrates the breast parenchyma. "This study evaluated the correlations between MIB-1, PhH3, and mitotic count in a defined area, focusing on invasive breast carcinoma." (PMID 24874299, 2014). "Proliferative activity of 101 invasive carcinomas of the breast on NCB and SES was assessed using mitotic counts on routine haematoxylin and eosin (H&E) sections and immunohistochemical markers Mib-1 and phosphorylated histone H3 (PPH3)." (PMID 20716163, 2010). "This patient was diagnosed with an invasive breast cancer in the upper outer quadrant of the right breast (TNM: pT1c pN0(sn) M0; estrogen and progesterone receptor expression positive; MIB1 25%; Her2/neu negative) and received breast conserving surgery in December 2015." (PMID 35884579, 2022).
left ventricular noncompaction (4 papers, 2022 to 2025). Left ventricular noncompaction (LVNC) is a rare cardiomyopathy characterized anatomically by prominent left ventricular trabeculae and deep intratrabecular recesses causing progressive systolic and diastolic dysfunction, conduction abnormalities, and occasionally thromboembolic events. "The MIB1 gene (“Mindbomb” gene) encodes the E3 ubiquitin-protein ligase MIB1, which regulates endocytosis of Notch ligands and has been associated with left ventricular non-compaction syndrome (OMIM 615092)." (PMID 35052463, 2022). "Mutations in MINDBOMB 1 (MIB1), encoding an E3 ubiquitin ligase of the NOTCH signaling pathway, cause left ventricular noncompaction cardiomyopathy (LVNC) in mice and humans, increasing the risk of arrhythmia and left ventricular dysfunction." (PMID 40334239, 2025).
leiomyosarcoma (4 papers, 2013 to 2021). An uncommon, aggressive malignant smooth muscle neoplasm, usually occurring in post-menopausal women. "Tumors of the PLS showed morphologically higher grade, and higher mindbomb E3 ubiquitin protein ligase 1 (MIB-1) labeling index than in ordinary leiomyosarcoma patients." (PMID 24947892, 2014).
lymphoma (4 papers, 2000 to 2021). A malignant (clonal) proliferation of B- lymphocytes or T- lymphocytes which involves the lymph nodes, bone marrow and/or extranodal sites. "MIB1 (Ki-67) staining is usually low, ranging from 10 to 30%, which correlates with the indolent nature of this lymphoma." (PMID 29740389, 2018). "The interfollicular high grade lymphoma infiltrate showed > 95% MIB1 immuno-reactivity while the neoplastic follicles displayed MIB1 immuno-reactivity in 20%-30% cells only." (PMID 21736761, 2011). "The expression of p27, pRb and the cell proliferation marker Ki-67 (MIB-1) was evaluated in lymphomas using immunohistochemistry." (PMID 11027429, 2000). "Three of the lymphomas were positive for human specific Ki67 (MIB1, Dako) indicating human cell origin, whereas the fourth was negative for the MIB1 antibody." (PMID 33802022, 2021).
schwannoma (4 papers, 2018 to 2025). A benign, usually encapsulated slow growing tumor composed of Schwann cells. "We evaluated the expression of COX2 in the yet largest cohort of 1048 vestibular schwannomas including 115 schwannomas of NF2 patients and compared the expression with demographic factors as well as tumor extension, MIB1 expression and the intake of COX2 responsive medication." (PMID 31291992, 2019). "More than half of the published case reports lacked the complete pathologic description of the schwannoma, and the differentiation between benign and malignant was not based on mitotic index, Ki-67, or MIB-1." (PMID 29970075, 2018).
viral infection (4 papers, 2012 to 2021). "Most TBK1 activity was restored 12 hr after viral infection in mib1−/− and MIB1/MIB2 double deficient MEFs." (PMID 23028469, 2012). "The immunity-related proteins Mib1, RhoB and Gbp5 became more abundant in macrophage lysosomes after treating with L. m, HSV-1 or VSV, while lysosomal Oasl2 (Viperin) was augmented by both virus infections." (PMID 28088779, 2017). "Following virus infection, activation of the RIG/MAVS pathway leads to TBK1 activation (presumably through phosphorylation by an upstream unknown kinase and ubiquitination by the E3 ligases MIB1/2 or Ndrp1) and to the disruption of its interaction with Optn and CYLD." (PMID 25923723, 2015).
adenoma (3 papers, 2002 to 2024). A neoplasm arising from the epithelium. "All lymphocytic infiltrate markers appeared higher in adenomas with an elevated proliferative index, with a significantly increased expression in CD45+ cell infiltrates in adenomas with high (MIB-1 > 3%) compared to low (MIB-1 ≤ 3%) proliferative indices (p = 0.0093)." (PMID 27655724, 2016). "In contrast, MIB-1 may differentiate adenomas from carcinomas of the adrenal cortex and may predict the biological behaviour of adrenocortical CA." (PMID 12085205, 2002). "MIB-1 positivity was 0.50±0.36% in normals, 0.54±0.08% in non-functioning adenomas and 0.54±0.08% in aldosterone-producing adenomas." (PMID 12085205, 2002). "Recently it has also been reported that MIB-1 expression differentiates benign from malignant adrenocortical tumours but not adenomas from normal cortex." (PMID 12085205, 2002).
anaplastic astrocytoma (3 papers, 2011 to 2013). "MIB-1 labelling has been shown particularly useful for differentiating between diffuse and anaplastic astrocytomas, but there is considerable overlap between the labelling index in these different tumours and diverging cutoff values have been proposed." (PMID 21559010, 2011).
astrocytic tumor (3 papers, 2013 to 2026). A glial tumor of the brain or spinal cord showing astrocytic differentiation. "Histologic sections showed an infiltrating astrocytic tumor with increased mitotic activity and elevated Ki67 (MIB1) labeling." (PMID 41736408, 2026). "It has been demonstrated that ADAM12m is selectively expressed in GBM tissues and that its expression levels is directly correlated with MIB1-positive cell index of the malignant astrocytic tumors." (PMID 26437223, 2015). "This study investigates the possible role of DJ-1 in the progression and prognosis of astrocytic tumors and emphasizes the relationship between DJ-1 and other important prognostic factors including the MIB-1 LI." (PMID 23902708, 2013).
cardiomyopathy (3 papers, 2019 to 2025). A disease of the heart muscle or myocardium proper.
cervical cancer (3 papers, 2021 to 2025). A primary or metastatic malignant neoplasm involving the cervix. "In a meta-analysis to assess the relationship between Ki-67/MIB-1 and cervical cancer (13 studies, 894 patients), it was found that this marker can be used as a predictor of prognosis due to its high correlation with the prognosis of the disease." (PMID 34830452, 2021). "Ki-67/MIB1 is considered to be a prognostic marker of cervical cancer; however, other features of the disease, such as the degree of malignancy, damage to the lymph nodes, and metastasis, may influence patient survival." (PMID 34830452, 2021). "A meta-analysis showed that cervical cancer patients with high Ki-67/MIB1 expression had shorter OS, suggesting that Ki-67/MIB-1 has prognostic value for OS in cervical cancer patients." (PMID 40309242, 2025).
congenital heart disease (3 papers, 2018 to 2024). A heart disease that is present at birth. "MIB1 mutations reduce Notch signaling activation and contribute to congenital heart disease." (PMID 37239988, 2023). "Genome-wide association studies and experimental mouse models implicate the MIB1 and GATA6 genes in congenital heart disease (CHD)." (PMID 39057643, 2024).
metastatic Disease (3 papers, 2013 to 2025). "Previous CMTs studies associated higher MIB-1 LI with other aggressive tumour features (larger size, infiltrative growth, high histological grade), higher risk of metastatic disease and decreased DFS and OS, strengthening our findings." (PMID 23289974, 2013).